INS (insulin)
Diseases named in the same sentence as INS in open-access papers (continued):
Sharing a sentence is not in itself a finding about the gene and the disease.
Insulin resistance (continued). "Second, we did not have data for plasma insulin concentrations to evaluate insulin resistance, such as homeostasis model assessment for insulin resistance." (PMID 34001028, 2021). "Similarly, in obese insulin-resistant rats, GRE administration upregulated relevant genes involved in the insulin signaling pathway and glucose metabolism, namely Insr, Irs1, Irs2, Pi3k and Ampk." (PMID 34208379, 2021). "In conclusion, TGFβ1 treatment in myotubes increased glucose uptake, suggesting that short term increased serum TGFβ1 or localised TGFβ signalling dysfunction are unlikely to induce insulin resistance via defects in insulin signalling in the skeletal muscle." (PMID 34707569, 2021). "The Janus kinase (JAK)/STAT3 pathway as well as the activation of STAT3 through AKT kinase and mTOR are the important insulin/IGF-1-stimulated, STAT3-mediated signaling pathways which are able to control immunosuppression, immunosenescence, and insulin resistance." (PMID 34476533, 2021). "However, the specific contribution of insulin signaling in SF1 neurons and its relationship to peripheral insulin resistance and glucose levels needs further investigation." (PMID 34201257, 2021). "Insulin resistance occurs when tissues, including the skeletal muscle, adipose tissue, and liver, do not respond well to insulin and is responsible for obesity, hyperglycemia, hyperlipidemia, and hypertension." (PMID 34684891, 2021). "A meta-analysis investigating the effects of HIIT on glucose regulation markers and insulin resistance in adults identified a reduction in HOMA-IR after HIIT, suggesting that HIIT may improve insulin sensitivity in those who are resistant." (PMID 33465123, 2021). "Additionally, an HFD is known to induce hyperinsulinemia and hyperglycemia, and increased serum insulin levels and HOMA-IR values are indicative of insulin resistance." (PMID 34257685, 2021). "We did not obtain fasting serum insulin in adolescents as this variable gives more objective measures of insulin resistance." (PMID 33388084, 2021). "Only 11.2% of the COVID-19 patients did not present insulin resistance, as indicated by the index based on fasting blood insulin and glucose concentrations (HOMA-IR)." (PMID 34957187, 2021). "The results presented in this study showed that TG and WC are the main metabolic syndrome factors that increased insulin resistance, β-cell function, insulin and HbA1c in non-diabetic FDRs of Type 2 DM." (PMID 34134670, 2021). "Significant differences were observed in fasting insulin, homeostasis model assessment of insulin resistance (HOMA-IR), TG, TC, LDL-C, non-HDL-C, TRLRs, ApoB, ApoCIII, ApoAI/ApoB and ApoCII/ApoCIII values between the two groups." (PMID 33967959, 2021). "UAL also has potential hypoglycemic effects, and we have shown that UAL treatment increased glucose uptake in insulin non-resistant myotubes as well as in a cellular model of insulin resistance in comparison with metformin used as positive control." (PMID 33920841, 2021). "Briefly, the authors found there was evidence that polyphenol consumption lowered fasting blood glucose levels overall but did not affect insulin levels or Homeostatic Model Assessment of Insulin Resistance (HOMA-IR) values." (PMID 34970150, 2021). "Moreover, the participants of the study had elevated insulin levels, showed high values on the HOMA-IR index of insulin resistance, and the serum level of S100B protein was significantly elevated compared to healthy volunteers." (PMID 34073816, 2021). "Another limitation of measurement was the lack of information on insulin resistance using insulin clamps, or surrogate measures such as HOMA-IR." (PMID 34260650, 2021). "Therefore, homeostasis model assessment of insulin resistance (HOMA-IR) index, calculated as the product of the fasting levels of glucose and insulin, is suggested as a robust marker for IR quantification." (PMID 33800541, 2021).
Insulin resistance (continued). "Another in vivo study showed that the administration of β-sitosterol significantly increased the levels of insulin, hemoglobin, and the PPAR-γ and GLUT4 proteins, alleviated insulin resistance, and decreased the plasma glucose levels in high-fat diet- and streptozotocin-induced diabetic rats." (PMID 33953784, 2021). "In TnTp38γ/δact mice at PD14, cardiac-specific overexpression of p38γ/δ increased blood glucose levels and insulin resistance but did not change blood insulin levels." (PMID 34758018, 2021). "There is a direct correlation between the degree of insulin resistance, defined by a decreased responsiveness to insulin and characterized by reduced glucose disposal in non-hepatic tissues, and the severity of NASH." (PMID 32443737, 2020). "Discrepant results were reported regarding the impact of INSTI on insulin sensitivity, some studies arguing for an improvement, and others for no change or even a worsening of insulin resistance." (PMID 31971958, 2020). "Considering the degree of insulin resistance, MHO-MetS patients that were insulin sensitive had a significantly better metabolic profile, not only compared to MUO, but also compared to insulin resistant MHO-MetS (e.g., patients classified as “healthy” according to MetS criteria)." (PMID 32731619, 2020). "Indeed, since insulin has been shown to suppress VLDL secretion, insulin resistance coinciding with NAFLD also enhances VLDL secretion." (PMID 33597924, 2020). "Fasting glucose levels showed main effect of time (p = 0.010), while insulin levels (p = 0.027) and insulin resistance, by HOMA-IR (p = 0.015) decreased in the TG, with no changes observed for the CG (p > 0.05 for all)." (PMID 33037261, 2020). "Plasma RBP4 concentrations in the first and second trimester were associated with fasting insulin, homeostasis model assessment for insulin resistance (HOMA-IR), and the quantitative insulin sensitivity check index (QUICKI) in the second trimester (all P < 0.001)." (PMID 31921323, 2020). "The term “insulin resistance” is defined as a pathological condition where metabolically active tissues do not respond to normal physiological concentrations of insulin, leading to glucose intolerance due to impaired insulin-receptor signaling." (PMID 33114711, 2020). "In other words, insulin sensitivity was well maintained as seen in other studies and that DRSP/EE combination might be considered neutral in its effect on insulin resistance, a major player of PCOS." (PMID 32106860, 2020). "In the case of brain insulin resistance, insulin possibly failed to stimulate the clearance of Aβ, which permits its buildup inside the neurons causing neurodegeneration or neuronal loss, as hallmarks of T3DM or brain insulin resistance." (PMID 32365816, 2020). "Patients with insulin resistance have significantly higher TG levels, higher low-density lipoprotein (LDL) cholesterol, and lower HDL cholesterol levels compared with those with normal insulin sensitivity." (PMID 32399348, 2020). "To test whether HuR-FKO mice developed insulin resistance in adipose tissue, we examined the phosphorylation of AKT in eWAT after insulin administration and observed decreased phosphorylation of AKT in the HuR knockout eWAT." (PMID 31924774, 2020). "Augmented release of lipolytic substrates such as non-esterified fatty acids (NEFAs) is critical for insulin resistance by impairing insulin-stimulated glucose uptake." (PMID 32316265, 2020). "This study aimed to explore insulin signaling regulatory pathway in skeletal muscle of the DEHP-induced insulin-resistant mice and to investigate potential therapeutic strategies for treating insulin resistance." (PMID 32802189, 2020).
Insulin resistance (continued). "BBR and SIRT1 show striking similarities in the regulation of insulin sensitivity involving the AMPK pathway and inflammatory response in adipose tissue, suggesting that BBR may depend on the Sirt1 pathway to improve insulin resistance." (PMID 33390968, 2020). "Furthermore, iNOS promotes deactivation of downstream nodes of insulin signaling pathways including Akt, IRS-1 and IR, inducing insulin resistance." (PMID 32429195, 2020). "Nevertheless, the fasting insulin levels in serum and insulin resistance measured by ipGTT in db/db mice were not affected by R. faecis treatment." (PMID 33020474, 2020). "It is therefore possible that HFF diet, administered for only 4 weeks, is able to induce adipose tissue insulin resistance, as well as brain inflammation and oxidative stress, but does not trigger impaired response to insulin in brain." (PMID 31991770, 2020). "Insulin promotes glucose uptake through a series of signaling events triggered by binding to the insulin receptor and activating IRS1 phosphorylation, and IRS1-PI3K signaling is suppressed during insulin resistance." (PMID 33292347, 2020). "ES-62 had no significant protective effect on the progressively developing IR, serum insulin levels and pancreatic β-cell function nor on the outcome of the Homeostatic Model Assessment of Insulin Resistance (HOMA-IR) test." (PMID 32163524, 2020). "The results of HE staining and insulin antibody immunohistochemistry showed that the area of insulin area (β cell dense area) in the HFD group was significantly increased because high glucose and high lipid intake induced insulin resistance and led to compensatory proliferation of islet β cells." (PMID 33551809, 2020). "Notably, the levels of miR-26a were inversely correlated with BMI, the subjects’ homeostatic model assessment index of insulin resistance (HOMA-IR), fasting blood glucose, and fasting insulin levels." (PMID 32092075, 2020). "Given that inflammation is the driving factor in the maturation of insulin resistance during obesity, T2DM and neurodegenerative diseases, including AD and PD, it is implied that AG enhances insulin sensitivity by suppressing systemic inflammation, hyperlipidemia and oxidative assault." (PMID 33381011, 2020). "Therefore, defects at the proximal level of insulin signaling that involve INSR, IRS1, PI3K, and Akt pathways are more evident in skeletal muscle insulin resistance, resulting in a decrease in insulin‐stimulated glucose uptake." (PMID 33038072, 2020). "In mice challenged with a high fat diet, FTY720 improves glucose tolerance, reduces plasma insulin, and increases insulin-stimulated glucose uptake, suggesting FTY720 may have therapeutic potential in treating insulin resistance." (PMID 31911836, 2020). "Furthermore, high-fat diet resulted in insulin resistance in osteoblasts, leading to a decrease in OCN activity and a decrease in insulin sensitivity in white adipose tissue and skeletal muscle." (PMID 33537005, 2020). "Existing studies had reported that JPXK prescription could increase fasting insulin (FINS), reduce insulin resistance (IR), and enhance islet cell function in diabetic rats, as associated with AMPK/mROC1/SAD-A signaling pathway." (PMID 33456489, 2020). "The glucose tolerance tests (GTT) and insulin tolerance tests (ITT) assays showed that the glucose tolerance and insulin resistance were markedly improved, and the expressions of IRS and PPARγ were upregulated in adipose tissue from MIFP1G/P1G mice fed with HFD." (PMID 32265835, 2020). "Moreover, exercise reduced fasting glucose and enhanced insulin sensitivity and pancreatic β-cell function, as determined by homeostasis model assessment (HOMA)-insulin resistance and HOMA-β indices, respectively." (PMID 32260278, 2020). "These ozone-induced glucose, lipid and protein metabolic changes were apparent without peripheral insulin resistance but impairment in pancreatic insulin secretion in response to glucose injection." (PMID 33004997, 2020).
Insulin resistance (continued). "Either the HOMA indices do not represent insulin resistance faithfully or the classically believed pathway of compensatory insulin response leading to hyperinsulinemic normoglycemic state is wrong according to this analysis." (PMID 33365205, 2020). "High C-peptide and high HOMA-IR suggest that large amount of insulin secreted from beta-cells did not compensate strong insulin resistance." (PMID 32005949, 2020). "Consumption of whey protein resulted in significant reduction of HbA1c (WMD: -0.15; 95% CI: − 0.29, − 0.01) insulin (WMD: -0.94; 95% CI: − 1.68, − 0.21) and homeostasis model assessment-estimated insulin resistance (HOMA-IR) (WMD: -0.20; 95% CI: − 0.36, − 0.05)." (PMID 32958070, 2020). "When insulin production does not overcome insulin resistance, possibly due to β-cell dysfunction, glucose intolerance and hyperglycemia occurs." (PMID 33114711, 2020). "Finally, by calculating the insulin resistance index (HOMA-IR), we found that the sensitivity of the GK rats to insulin was increased in the BD3526 group (P = 0.0088)." (PMID 33424779, 2020). "We have observed a negative correlation between the ANGPTL8, insulin and homeostasis model assessment of insulin resistance (HOMA-IR)." (PMID 32069954, 2020). "One week of treatment with tesaglitazar-loaded liposomes did not significantly lower levels of fasting blood insulin or glucose, but did improve indices of insulin resistance." (PMID 31903139, 2020). "Third, the homeostatic model assessment of insulin resistance was not analyzed and compared with TyG index because insulin levels were not measured in the PARADIGM registry." (PMID 32682451, 2020). "In addition, the studies have shown that adiponectin treatment enhances insulin-stimulated glucose phagocytosis by activating AMPK in primary adipocytes of rats, which has the potential to improve insulin resistance and type II diabetes." (PMID 32937822, 2020). "The phenomenon of insulin toxicity partly arises from the fact that there are additional cellular responses to elevated insulin levels which are not toned down during insulin resistance." (PMID 32819363, 2020). "The improvement of insulin-dependent glucose uptake in such conditions indicates that TNF-α is an important mediator of insulin resistance through negative influence of this cytokine on important sites of the insulin signaling pathway." (PMID 33322719, 2020). "Insulin inadequately inhibits glucagon secretion in insulin-resistant alpha cells, resulting in fasting hyperglucagonemia, which promotes fasting hepatic glucose production and IFG, especially in the setting of hepatic insulin resistance." (PMID 32774668, 2020). "In contrast, a meta-analysis of cocoa and chocolate in terms of resistance or sensitivity to glucose and insulin is likely to show beneficial effects on insulin resistance (IR) but not on glucose levels." (PMID 33266002, 2020). "The CAF-H2 rats showed higher insulin sensitivity, as measured by the R-QUICKI index, as compared to CAF-V rats, which is line with the decrease in FFA observed in these animals due to their relationship with insulin resistance." (PMID 31963315, 2020). "Insulin resistance is characterized by the impairment of PI3K-dependent signaling pathways without any effect on other insulin dependent pathways." (PMID 32235782, 2020). "ProINS-Tf also demonstrated a better glucose-lowering effect than native insulin, even with a much lower dose and less frequent injections, in non-obese diabetic mice with insulin resistance symptoms." (PMID 32382087, 2020). "The PI3K/AKT pathway is critical for insulin signaling; hence, any defect in AKT/PKB pathway along with the downstream molecules may lead to insulin resistance." (PMID 32131495, 2020). "The most important mechanism of insulin resistance is that the increased FFA levels inhibit tyrosine phosphorylation of IRS-1, thereby inducing inactivation and inhibiting GLUT4 translocation to the cell surface, down-regulating insulin signaling." (PMID 33266423, 2020).
Insulin resistance (continued). "Thus, IL-6- or TNF-α-dependent insulin resistance is mediated, at least in part, by the induction of SOCS proteins in insulin target cells." (PMID 33255404, 2020). "Though these differences in C-peptide are clear, no normative data defining fetal insulin resistance currently exists, e.g., in terms of C-peptide, insulin, or HOMA-IR “cut-off points”." (PMID 32778645, 2020). "In individual patients with FPLD insulin secretion disruption or low dipeptidyl peptidase 4 (DPP4) levels were observed in addition to insulin resistance, suggesting the use of glucagon-like peptide 1 receptor agonists (GLP1) to improve glycemic control and reduce the high insulin demand." (PMID 33233602, 2020). "With the progression of the disease, dysfunctional β-cells do not release sufficient insulin to compensate for peripheral insulin resistance, leading to the development of overt T2DM." (PMID 33329397, 2020). "Thus, we believe the insulin dosage used in an ITT should be personalized and increased in patients who are overweight, obese or with insulin resistance." (PMID 32328036, 2020). "Although we did not determine insulin resistance directly, it is possible that the increase in insulin secretion in the HFS-fed rats was partially due to the increase in 12αOH BA concentration in the enterohepatic circulation regardless of insulin sensitivity." (PMID 31941510, 2020). "Although HMH2 and HMH3 reduced early time point glucose excursion during the OGTT, they did not reverse insulin resistance in obese mice (no changes of insulin production during OGTT and glycemia during the ITT)." (PMID 33105775, 2020). "Insulin-sensitive MHO individuals tend to have lower visceral and intrahepatic fat accumulation than their MUHO counterparts, providing further evidence that these fat depots contribute to insulin resistance." (PMID 32158768, 2020). "Measuring amino acids and conventional metabolites has revealed changes in pregnant women with a higher insulin resistance and high blood glucose levels that resemble the changes seen in non-gravid, insulin-resistant populations." (PMID 33335512, 2020). "CRP has been shown to play an active role in hepatic insulin resistance, at least partly through impairment in insulin signalling, independent of IL-6." (PMID 32828613, 2020). "Surprisingly, no clear evidence for a state of insulin resistance or the antilipolytic effect of insulin was found in large adipocytes, which was a clear confirmation of the results found in the in vivo study, in which exactly the same animals had been used." (PMID 32823892, 2020). "Insulin resistance predisposes to the development of T2DM as the pancreatic β-cells start to shut down the production of insulin and no longer create enough insulin to control blood sugar level; this phenomenon leads to hyperglycemia." (PMID 32879653, 2020). "Furthermore, evidence was recently provided that CB1 activation induced by an HFD suppresses the insulin-dependent phosphorylation of Akt through IRS-1 phosphorylation at Ser-307, thereby mediating the emergence of insulin resistance." (PMID 32859125, 2020). "Pearson correlation analysis showed that GA was positively correlated with Fasting plasma glucose (FPG), Fasting insulin (FINS) and Insulin resistance index(HOMA-IR) levels (P<0.001), while adiponectin was negatively correlated with FPG FINS and HOMA-IR levels (P<0.001)." (PMID 33083291, 2020). "The glycemic profile [fasting glucose, glycated hemoglobin (HbA1c), homeostatic model assessment-insulin resistance (HOMA-IR), quantitative insulin sensitivity check index (QUICKI)], plasma and erythrocyte malondialdehyde (MDA), total antioxidant capacity (TAC), and ubiquinone status were measured." (PMID 32899227, 2020). "Endoplasmic reticulum (ER) stress may play a role in the development of insulin resistance, and ER stress can activate JNK which in turn suppresses insulin signaling." (PMID 32961883, 2020).